ENSG00000284554 (novel protein)
Gene: Protein-coding gene on chromosome 22 (39,014,363 to 39,033,276, forward strand). Ensembl gene ENSG00000284554.
Genetic constraint (gnomAD): Loss-of-function variants: 37 observed, 47.31 expected, observed/expected ratio (o/e) 0.78, 90% interval 0.6 to 1.03. Missense variants: 496 observed, 509.24 expected, observed/expected ratio (o/e) 0.97, 90% interval 0.9 to 1.05. Synonymous variants: 175 observed, 184.15 expected, observed/expected ratio (o/e) 0.95, 90% interval 0.84 to 1.08.